TNF (tumor necrosis factor)
Diseases named in the same sentence as TNF in open-access papers (continued):
Sharing a sentence is not in itself a finding about the gene and the disease.
tumor (continued). "Th1 cells produce tumor necrosis factor alpha (TNF-α), interferon gamma (IFN-γ), interleukin (IL)-2 and IL-12 to mediate antitumor effects, while Th2 cells produce IL-4 and IL-10 which favor tumor growth." (PMID 35805995, 2022). "It has been demonstrated that altered tumor microenvironment or inflammation induces FAP expression through stimulation of cytokines such as TGF-β1 and TNF-α, chemical substances, or physical stimulants." (PMID 35222418, 2022). "In DCs, tumor-derived exosomal miR-203 reduces TLR4 expression and inhibits the release of downstream cytokines (e.g., TNF-α, crucial to DCs maturation, and IL-12, required for Th1 differentiation), thus promoting cancer immunosuppressive microenvironment." (PMID 35663957, 2022). "CD103+ CD4+ T cells exhibit an immunosuppressive phenotype and high retention capacity in GC tumor tissues, leading to CD8 + T cell dysfunction, and granzyme B (GZMB), interferon-γ (IFN-γ), tumor necrosis factor α (TNF-α), and perforin (PRF-1) reduction." (PMID 36341377, 2022). "Lymphocytes are often able to inhibit tumor proliferation and metastasis, and kill tumor cells through their immune function (secrete interferon gamma (INF-γ) and tumor necrosis factor (TNF-α))." (PMID 35932022, 2022). "Granulocyte-macrophage colony-stimulating factor (GM-CSF), tumor necrosis factor alpha (TNF-α), and transforming growth factor-beta 1(TGFβ1) promote tumor cell proliferation and survival." (PMID 36387244, 2022). "TNFα-CSG treatment of mice bearing ALB-Tag HCC increased intratumoral immune cell infiltrates, reduced ECM content and improved tumor perfusion." (PMID 35273916, 2022). "With either TNF-α or IFN-γ production deceased or interrupted, anti-tumour effects are dramatically decreased." (PMID 35557940, 2022). "For example, a report showed that macrophages produced higher levels of TNF, IL6, and IL‐1β after stimulation with H. capsulatum, whereas a different report showed that macrophages treated with dying tumor cells exhibited M2 phenotype." (PMID 35037422, 2022). "Overall, cytokine levels were lower in the twin-tumor model, but all treatments with mLOAd703 resulted in higher levels of IFN-γ, TNF-α, and IL-27p28 as observed before." (PMID 35141399, 2022). "Coupled with SPIONs, the capacity of TNF-α to bind to its receptor TNFR I was significantly enhanced, with activation of the TNFR I-mediated apoptotic pathway and inhibition of tumour growth in melanoma." (PMID 36167539, 2022). "A recent study based on flow cytometry found that an increase in tumor-infiltrating plasmocytoid cells promotes OSCC proliferation, primarily by TNF-α/NF-κB/CXCR-4 pathway." (PMID 35634436, 2022). "Impaired production of IFN-γ, tumor necrosis factor (TNF), IL-2, and a high expression of coinhibitory receptors are observed, which compromises their ability to fight against infections and tumor cells." (PMID 35055124, 2022). "Due to their critical roles in anti-tumor immunity, it is of great interest to know how gene expression or pathway enrichment is differentially regulated by IFN or TNF stimulation." (PMID 34534350, 2022). "Marimastat inhibits the cleavage of TNF-α and CD44 and reduces the invasion of tumor cells with an IC50 of 4.75 μM." (PMID 36466812, 2022). "In contrast to this observation, it has been reported that mice that received anti-TNF added to combined CTLA-4 and PD-1-blockade had a higher rate of tumor control and survival than mice that were treated with CTLA-4- and PD-1-blockade only." (PMID 35538491, 2022). "In lung cancer, iron-loaded TAMs enhance ROS production and pro-inflammatory cytokines (TNFα and IL6) to induce tumor cell death." (PMID 36158661, 2022). "T cells then transport to the tumor site and kill tumor cells through cytotoxicity against homologous antigens and secretion of cytokines such as IFN-γ and TNF-α." (PMID 35418151, 2022).
tumor (continued). "In patients with cancer, proinflammatory cytokines such as interleukin (IL)-1, IL-6, tumor necrosis factor alpha (TNF-α), interferon-alpha (IFN-α), and interferon-gamma (IFN-γ) are released by the tumor or the host’s immune system in reaction to the tumor." (PMID 35455957, 2022). "Reportedly, TNF-α exhibits bidirectional effects in the TME, inducing tumorigenesis as well as tumor suppression." (PMID 36505472, 2022). "Two effector CD4+ T cells, characterized by high expression of either IFNγ and TNF or GZMA and GZMK, showed an anti‐tumour function." (PMID 35184398, 2022). "TNF-α mediates distinct signaling pathways through two structurally distinct receptors, TNFR1 and TNFR2, and thus has distinct functions in the tumor environment." (PMID 35494080, 2022). "Other cytokines, such as TNF-α, IL-6, CCL22, and TGF-β, can also promote the retrodifferentiation of tumor-derived hepatocytes into stem/progenitor cells." (PMID 35449193, 2022). "In combination with chemotherapy or through administration locally at the tumor site, Nr-CWS prolongs the survival of patients with advanced cancers and increase the levels of cytokines, such as IL-1, IL-6, TNF-α and IFN, in tumor tissue." (PMID 36110249, 2022). "Analysis of the tumor immune infiltrate showed that DMXAA monotherapy up-regulated production of anti-tumor cytokines (i.e., IFNγ, Granzyme B, and TNFα) in both CD8+ and CD4+ T cells, which was further enhanced by combining with olaparib therapy." (PMID 35641483, 2022). "Effector tumor-specific T cells amplify and move through blood flow into the tumor microenvironment (TME) to induce tumor destruction through cytotoxicity and the production of certain cytokines [e.g., interferon (IFN)-γ and tumor necrosis factor (TNF)-α]." (PMID 35990683, 2022). "The combination of inosine supplementation and anti-PD-L1 mAb therapy increased tumor infiltrating T cells and IFN-γ and TNF-α expression compared with anti-PD-L1 mAb therapy alone." (PMID 35956752, 2022). "TNF-α triggers the disruption of tumor vasculature, reduces intra-tumoral interstitial fluid pressure (IFP) and promotes the flow of blood to tumors, and TNF-α is used to improve drug delivery to tumors." (PMID 36330464, 2022). "CD4+ T cells contain two diverse subsets of helper T cells, namely, Th1 cells, which produce TNF-α, IFN-γ, IL-2, and IL-12 to mediate antitumor effects, and Th2 cells, which generate IL-4 and IL-10 and foster tumor growth by suppressing the host immune system." (PMID 36212483, 2022). "Tumor necrosis factor (TNF)-related apoptosis-enhancing ligand (TRAIL), Fas ligand (FasL) and cytokines such as IFN- are involved in tumor cell apoptosis." (PMID 35617812, 2022). "In both CRC subtypes, the pro-inflammatory cytokines IL1-β, IL-6 and TNF upregulate the chemokines CXCL-1/2/3/5/6/8 in CAFs, monocytes and cancer cells; this attracts CXCR1/2-positive neutrophils to the tumor." (PMID 36611932, 2022). "For one thing, SALL4 is an underlying biomarker that activates signaling pathways and oncoproteins that promote tumor progression including Wnt/β-catenin, PI3K/AKT, Notch signaling pathway, and OXPHOS, as well as Bcl-2, TNF-α, and IFN-γ." (PMID 35216168, 2022). "The treated CAR-T cells exhibited better anti-tumor efficacy, and more IFN-γ+ TNF-α+ T cells infiltration was found in tumors." (PMID 35956752, 2022). "The other was to directly connect with tumor cells through the MIF and TNF pathway to play a tumor-promoting role." (PMID 36479092, 2022). "Previous studies have shown that the nano-gold-TNF complex can significantly prevent uptake of a reticuloendothelial system (RES) and can be quickly targeted to tumor tissues within 4 h of administration." (PMID 35664731, 2022). "Our in vivo studies demonstrated that TNFα pre-treated BCSC1 and BCSC2 were able to enhance the capacity of the stromal cells to invade the primary tumor." (PMID 36290384, 2022).
tumor (continued). "Therefore, it is hard to say whether the shortened survival is due to over-inhibition of immune activation against tumor growth, or negative effects solely caused by anti-TNF therapy." (PMID 35844550, 2022). "Typically, cytokines mattering immune activation and CAR‐T replication (IL‐2, IL‐6, TNF‐α, and IFN‐γ) are drastically increased, hinting at the replication and function maintenance of CAR‐T cells for executing anti‐tumor actions." (PMID 36156442, 2022). "designed ChPD1-T cells for recognizing and damaging tumor cells by secreting inflammatory factors such as IL2, IL-17, IL-21, IFN γ, TNF, and GM-CSF and decreasing the inflammatory suppressor cytokine IL-10." (PMID 35935930, 2022). "The localized delivery of TNF-α induced vascular leakage in the tumor, reduced the tumor interstitial fluid pressure (IFP), and enhanced tumor uptake." (PMID 35213967, 2022). "The biological activity of GEN1046 on T cells was reflected by increases in IFNγ, TNFα, IL2, and CXCL10 in peripheral blood in MC38-hPD-L1 and MC38-WT tumor–bearing mice." (PMID 35176764, 2022). "Inflammatory cytokines such as IL-6, IL-21, IL-1β, and TNF-α diminish the cytotoxic capacity of immune CD8+ T cells to produce IFN-γ, which plays a main role in angiogenesis and MHC expression—tumor recognition." (PMID 35681689, 2022). "Reduces tumor weight, increases the levels of IFN-γ, TNF-α, GZMB and the expression of CLCA3, TFF3, AGR2, Zg16, Pla2g10, Guca2a." (PMID 35548468, 2022). "The exosome-coated BPQDs with NIR not only showed prophylactic effect, but also revealed therapeutic effect to enhance the infiltration of lymphocytes, such as CD4+ and CD8+T cells, into the tumor site and the secretion of IFN-γ and TNF-α in LLC-bearing mice." (PMID 35859703, 2022). "Meanwhile, IL-1b and TNF-α, as stimulators of NF-κB pathway, both enhanced tumorigenesis in CRC, whereas blockade of the NF-κB pathway inhibited tumor growth." (PMID 35596224, 2022). "Another study confirmed that IL-18 promoted the secretion of TNF-α and IFN-γ, which synergistically enhanced the cytotoxic function of tumor-infiltrating lymphocytes with IL-12 in GC, and produced an anti-tumor effect." (PMID 36185234, 2022). "Patients with tumor progression and resistance to treatment presented then with an increasing plasma rate of IL17A and TNF after the first infusion of pembrolizumab, in comparison to patients with DCB." (PMID 35794623, 2022). "The diverse activities of TNF-α led to the simultaneous and paradoxical pursuit of TNF-α as an anti-tumor strategy." (PMID 35406450, 2022). "The activated mast cells also produce IL1β, IL6, IL8, IL13, TGFβ, TNFα, PDGF, and VEGF for promoting tumor growth and metastasis directly, and also indirectly by provoking angiogenesis and immune chaos." (PMID 36211375, 2022). "Enzyme immunoassay analysis showed decreased TNFα in tumors in the distal part of the colon and increased IL10 in proximal tumors and in non-tumor tissues." (PMID 36555251, 2022). "Animal experiments have shown that tumor-derived factors such as IL-6, CXCL16, IFNγ, TNFα, and IGFBP-3 positively regulate the expression of CD38, and high expression of CD38 can enhance the immunosuppressive and tumor-promoting capacity of MDSCs." (PMID 36119033, 2022). "To determine the impact of local tumor immunomodulation on the systemic immune response, we analyzed the ability of splenocytes to produce IFN-γ and TNF-α ex vivo." (PMID 36046055, 2022). "As a critical activator in inflammation and cancer, NF-κB controls the release of TNF-α, CCL-2, various inflammatory factors, and tumor-related genes." (PMID 35955463, 2022). "A range of cytokines, including TNF, RANKL, IL-1, and IL-6, induce inflammation and promote tumor cell metastatic capacity through altering dissemination and colonization in distant metastatic lesions." (PMID 36090985, 2022).
tumor (continued). "Examination of cytokine levels in tumor-bearing mice on post-inoculation day 21 showed that inoculation of ATX-KO B16-F10 cells led to a selective increase in IFNγ and TNFα levels only in Sftpc-KO mice." (PMID 35326737, 2022). "NK cells, with the potent ability to kill tumor cells, induce remodeling of the oral TME via IFN-γ and TNF-α, as well as prevent tumor growth and metastasis." (PMID 36212161, 2022). "To further reveal the relationship between FR4 positive cells and tumor immune microenvironment, we used 90 ESCC data from the TCGA public database to analyze PD-1, PD-L1, IL-2, IL-7, and levels of IFN-γ and TNF-α." (PMID 35756495, 2022). "This multifunctional strategy upregulated the maturation of DCs, increased the secretion levels of TNF-α and IFN-γ, promoted the Th1 immune response, and increased tumor T-cell infiltration with proper CD8+ CTLs/Tregs and effector CD4+ T cells/Tregs ratios." (PMID 35335881, 2022). "NF-κB inhibition—TNFα is one of the proinflammatory cytokines which can trigger the activation of NF-κB pathway, crucial during CRS, whose dysfunction is involved in tumor development." (PMID 36289890, 2022). "Inflammation-related mediators released by tumor cells inhibit T helper 1 (Th1) cells, e.g., IL-2, Interferon-gamma (INF-γ) and TNF-α, and induce Th2 peripheral cytokines, e.g., IL-10, IL-6 and IL-4." (PMID 35057010, 2022). "NK cells secrete a wide variety of anti-tumor cytokines such as IL-10, IL-5, IL-13, GM-CSF, IFN-γ, TNF-α." (PMID 36253762, 2022). "These M1 macrophages orchestrate protective anti-tumor immune responses through the expression of nitric oxide synthase (NOS2) and TNF-α." (PMID 36297535, 2022). "Astrocytes are also activated by tumor cell-derived TGLI1, MIF, IL-8, IL-1β, and TNF-α, as seen in lung and breast cancer brain metastases." (PMID 36291792, 2022). "Tumor tissues showed obviously higher expression levels of NLRP1, IL18, TNF, and CASP4 than did the normal tissues." (PMID 35785176, 2022). "Integrin αvβ3 enhanced angiogenesis which is induced by basic fibroblast growth factors and tumor necrosis factor α, and integrin αvβ5 enhanced VEGF-induced angiogenesis and tumor metastasis." (PMID 35042954, 2022). "TNF-α is a cytokine that binds to TNFRSF1A/TNFR1 and TNFRSF1B/TNFBR, is secreted by macrophages and induces tumor cell death and other inflammatory mediators and proteases that orchestrate inflammatory responses." (PMID 35453307, 2022). "Consistent with previous studies, DDR can lead to the production of cancer-related inflammation, which induces TME-secreting factors such as TNF, IL-1, CCL2, and CXCL8; and activates transcription factors of NF-Κb, Stat-3, thus promoting tumor proliferation." (PMID 35413945, 2022). "Overall, NEO increased the proinflammatory function of tumor-infiltrating CD4+ T cells, with enhanced TNF-α and IL-2 but reduced IL-4 and IL-10 expression." (PMID 36509285, 2022). "Taken together, we hypothesized that although the administration of TNFα to MSCs and joint cells such as chondrocytes and synovial cells induces inflammatory reactions, their CM may act as the anti-inflammatory agent in the same manner as the anti-tumor proteome." (PMID 35804814, 2022). "Gitr+CD8+ T cells isolated from both spleen and tumor of αCD40-treated Batf3–/– mice exhibited higher levels of proinflammatory markers, including IFN-γ and TNF-α." (PMID 35393950, 2022). "A reduction in TNF-α mRNA levels was also observed in the GSE44076 dataset between malignantly transformed tissue and control subjects’ healthy mucosa and between tumor-adjacent and healthy mucosa." (PMID 36429712, 2022). "During tumor cell elimination, effector T cells, including CD4+ helper (Th) and CD8+ cytotoxic lymphocytes (CTLs), secrete cytokines IFN‐γ and TNF‐α to induce tumor cell death and recruit other effector cells." (PMID 35782339, 2022).
tumor (continued). "It produces a series of chemokines and cytokines that regulate immunity, including IFN-γ, TNF, IL-6, and CCL5, which have the function of regulating immune response and anti-tumor and are related to the improvement of the overall survival rate of patients." (PMID 36686745, 2022). "The combined treatment with a dual system isoDGR/Au/TNF and DOX lead to a significant tumor growth inhibition compared to free DOX." (PMID 36430214, 2022). "Therefore, missing or mutated SAMHD1 might contribute to a pro-tumor microenvironment, as the cells are not able to correctly downregulate inflammatory signals like TNF-α in the absence of SAMHD1." (PMID 34480199, 2022). "They stimulate tumor progression by promoting tumor cell invasion, migration (MMPs), production of anti-inflammatory cytokines (TGF-beta, IL-10) and angiogenic factors (VEGF, TNF-alpha, HIF-1)." (PMID 35804950, 2022). "In line with this, our results showed that the PAR1 inhibitor suppressed TNF-α and CXCL1 production and rKLK6-promoted tumor growth and metastasis in the xenograft model, suggesting that PAR1 plays a critical role in KLK6-mediated malignant progression." (PMID 36552865, 2022). "As an activator protein in the NF-κB and TNF (tumor necrosis factor), TRAF3IP2 is believed to play a clear role in tumor initiation and progression." (PMID 35897085, 2022). "An increase in GrB+ and IFNγ+TNFα+ CD4+ T cells with fewer central memory T cells and surprisingly fewer IFNγTNFα+ CD8+ T cells in tumor, with a decreased presence of myeloid, notably HLA-DRlo cells, correlated with smaller tumors." (PMID 36419897, 2022). "MSC releases several non-coding RNAs and anti-cancer molecules such as tumor necrosis factor (TNF), TNF-related apoptosis-inducing ligand (TRAIL), and interferon-β (IFN-β) via exosomes that acts as pro-apoptotic or tumor suppressor factors." (PMID 35511336, 2022). "Previous immune-related analyses in this paper showed that CHMP4C, TNF, and GZMB are all closely related to the tumor immune microenvironment." (PMID 35574296, 2022). "IFN-γ and TNF-α are released by immune effector cells such as activated CAR T cells and by lysis of tumor cells and induce activation of other immune cells and endothelial cells." (PMID 35845425, 2022). "On a mechanistic level, we found TNFα-mediated activation of NF-κB RELA and/or c-REL depending on the tumor type." (PMID 36361720, 2022). "We found that TNF pathway inhibitors treatment (IKK-16 and JSH-23) diminished the tumor growth-promoting effect induced by CBX7 knockdown in both 786-O and A498 cells." (PMID 35342353, 2022). "Neutrophils secrete high levels of TNF-α and TGF-β, which significantly stimulate tumor cell migration and invasion." (PMID 36555469, 2022). "For further confirmation of our TME flow cytometry data showing CD4 and CD8 T-cell activation, we found an increase in Th1 pro-inflammatory cytokine (IFNγ, TNFα, IL-2, and KC/GRO) levels in the tumor lysate." (PMID 35651802, 2022). "The combination of 5-FU with ICB augmented an inflammatory tumor microenvironment with markedly increased CD8+ T cell activation and upregulation of IFNγ, TNFα and IL-1β signaling." (PMID 35634282, 2022). "To understand the regulation of Blimp-1 expression in keratinocytes, we tested several agents including tumor promoter PMA, TLR4 ligand lipopolysaccharide (LPS), cytokine TNF-α, ROS stressors H2O2 and UVB in human HaCaT keratinocytes." (PMID 35185556, 2022). "Once in the TME, OrfV infection increased the activation status and release of TNF-α by recruited CD101− neutrophils, which we later observed to mediate the overall neutrophil cytotoxicity against the target tumor cells." (PMID 36139433, 2022).